FAM187A (family with sequence similarity 187 member A)
Tractability: Antibody: UniProt predicts a signal peptide or a membrane-spanning region.
Gene: Protein-coding gene on chromosome 17 (44,903,433 to 44,905,390, forward strand). Ensembl gene ENSG00000214447.
Subcellular location: Membrane
Subcellular location (Human Protein Atlas): Acrosome
Gene Ontology:
Cellular component: membrane
Genetic constraint (gnomAD): Loss-of-function variants: 6 observed, 10.5 expected, observed/expected ratio (o/e) 0.57, 90% interval 0.31 to 1.13. The upper end of that interval is the gene's LOEUF score, 1.13, which puts it in group 4 of 6, group 1 being the genes least tolerant of losing a copy. Missense variants: 463 observed, 554.72 expected, observed/expected ratio (o/e) 0.83, 90% interval 0.77 to 0.9. Synonymous variants: 221 observed, 220.74 expected, observed/expected ratio (o/e) 1, 90% interval 0.9 to 1.12.
Homologues: Orthologues: macaque FAM187A (96% identical), pig FAM187A (87% identical), rabbit FAM187A (85% identical), dog FAM187A (84% identical), rat FAM187A (83% identical), mouse Fam187a (79% identical). Paralogues in human: FAM187B (17% identical).
Diseases named in the same sentence as FAM187A in open-access papers:
FAM187A is named in the same sentence as 1 disease in open-access papers, as found by Europe PMC text mining. Sharing a sentence is not in itself a finding about the gene and the disease.
FAM187A shares sentences with these, for which no sentence is quoted: neurological disease (1 paper).